HIF1A (hypoxia inducible factor 1 subunit alpha)
Diseases named in the same sentence as HIF1A in open-access papers (continued):
Sharing a sentence is not in itself a finding about the gene and the disease.
breast cancer (continued). "As research and development of drugs targeting HIF-1α are primarily based on its mechanism of action, exploring this aspect of breast cancer drug resistance is of great significance to the development of related drugs." (PMID 36003773, 2022). "In breast cancer, other studies reveal miR-210 is regulated by hypoxia via HIF-1α/VHL transcriptional system." (PMID 35346372, 2022). "We next investigated the effect of HIF-1α on ACE2 expression in drug-resistant breast cancer cells (468/EPR cells)." (PMID 36335375, 2022). "It is part of a pre-defined gene set under the regulation of hypoxia inducible factor 1 alpha (HIF-1α) in breast cancer and there is a positive correlation between the expression of HIF-1α and MCU in-vitro seemingly found also in clinical data." (PMID 35163823, 2022). "Tumor hypoxia has been extensively demonstrated in breast cancer and expression of HIF1α represents an independent factor for poor prognosis in patients with lymph node-negative and -positive breast cancer, including several different subtypes." (PMID 36077517, 2022). "In breast cancer cells, overexpressed miR-29a-3p promotes the repression of HIF1α (hypoxia-inducible factor 1 subunit alpha) protein, the downstream mTOR effector." (PMID 36430972, 2022). "Opioids were shown to promote tumor angiogenesis in a breast cancer cell by stimulation of δ-opioid receptors in breast cancer cells, leading to activation of HIF-1α and expression of COX-2 via PI3K/Akt stimulation." (PMID 35681664, 2022). "Together, these clinical data show that HIF1α mediated hypoxic crosstalk with the estrogenic signaling correlates with poor overall survival of patients with in ERα-positive breast cancers." (PMID 36230857, 2022). "For example, the transmission of long non-coding RNA stabilizing HIF-1α under normoxia in breast cancer cell line MDA-MB-231 was reported." (PMID 36139678, 2022). "In contrast, we did not detect any correlation between DLEU1 and HIF-1α levels in breast cancer or the effect of shDLEU1 in altering HIF-1α expression, suggesting that their crosstalk is through physical interaction, but not expressional regulation." (PMID 35853854, 2022). "In breast cancer cells, HIF-1α is required for upregulation and secretion of the pro-tumorigenic cytokine Stem Cell Factor (SCF) by EGF." (PMID 35158804, 2022). "This study provides mechanistic insight into the anticancer activity of plumbagin in breast cancer cells under hypoxic conditions by abolishing HIF-1α at transcription and post-translational modifications." (PMID 36080483, 2022). "For example, HIF-1α signaling selectively supports breast cancer proliferation in the brain, which has been validated in vivo." (PMID 36003773, 2022). "SIAH2, which is closely related to the progression of breast cancer, has been reported to affect the stability of HIF-1α." (PMID 35309179, 2022). "As hypoxia is a key feature of breast cancer progression, the present study investigated the effects of plumbagin on HIF-1α expression under hypoxic conditions, and the potential molecular mechanisms in MCF-7 cancer cells." (PMID 36080483, 2022). "It was reported that circular RNA arose from HIF1A gene that was overexpressed in breast cancer tissues and sEVs from the plasma of breast cancer patients." (PMID 36212432, 2022). "Reduction of FIH1 increased the expression of HIF-1α, growth of breast cancer stem cells, and promoted the chemotherapy resistance." (PMID 36226048, 2022). "Hypoxia showed a central role in promoting resistance acquisition, as the blocking of HIF‐1α partially restored drug sensitivity in both breast cancer subtypes and decreased the molecular alterations induced by treatment." (PMID 34109737, 2022). "One study showed that fibroblasts transformed with constitutively active HIF-1α mutant promote the in vivo growth of co-injected MDA-MB-231 breast cancer cells via enhanced aerobic glycolysis and paracrine production of nutrients." (PMID 35884382, 2022).
breast cancer (continued). "Parkin has been shown to downregulate HIF1A via proteasomal degradation in breast cancer leading to inhibition of its metastasis, and similarly Parkin has been reported to downregulate HIF1A while upregulating HIF3A in GBM." (PMID 36552827, 2022). "HIF-1a not only mediates breast cancer angiogenesis but also leads to its metastasis, drug resistance, and poor prognosis." (PMID 36003773, 2022). "Acriflavine, a HIF-1α dimerization inhibitor, has also been reported to enhance the antitumor activity of sunitinib in 4T1 breast cancer models." (PMID 36003773, 2022). "A series of animal transplant tumor experiments have displayed that silencing the HIF1α pathway inhibits lymph nodes and lung metastases in breast cancer." (PMID 36473847, 2022). "Both ipsilateral and any breast cancer recurrence were more frequent in women with HIF-1α-positive primary tumours (hazard ratio, HR0–5 yrs1.9 [1.3–2.9], p = 0.003 and HR0–5 yrs = 2.0 [1.5–2.8], p < 0.0001)." (PMID 35140341, 2022). "First, in addition to HIF-1α, HIF-2α has also been associated with histological grade, Ki67 expression, and multidrug resistance in breast cancer." (PMID 36003773, 2022). "The decrease in available miR-106a-5p stabilizes STAT3 mRNA and activates HIF-1α, inducing proliferation in breast cancer cells." (PMID 35626715, 2022). "4-trimethylaminobutyraldehyde dehydrogenase (ALDH1A1), a subtype of aldehyde dehydrogenase, is associated with the self-renewal, metastasis, and resistance of cancer cells, is regulated by HIF-1α in breast cancer." (PMID 36014432, 2022). "This is largely due to the fact that it is the anesthetic option that least stimulates the expression of HIF-1α, whose blood level after surgery is proportionally related to the development of short-term breast cancer metastases." (PMID 35252243, 2022). "The results revealed that HIF-1α staining was approximately 11-fold increase in brain tumors in comparison with that in mammary tumors." (PMID 36003773, 2022). "The breast cancer stemness marker ALDH1A1 activates ALDH1A1/HIF-1α/VEGF axis through retinoic acid conduction, upstream HIF-1α is activated, induces VEGF expression and release, and promotes tumor angiogenesis." (PMID 36387165, 2022). "Isoliquiritigenin also demonstrated its efficacy to inhibit cell proliferation and migration of breast cancer by promoting HIF1A proteasome degradation." (PMID 35409008, 2022). "Dox/ONB significantly inhibited HIF-1α activity and increased ROS production to enhance the antitumor effect of doxorubicin under hypoxia in breast cancer cells." (PMID 36532768, 2022). "We would also like to note that recent reports from our laboratory have also reported that PHD-2 works as a tumor suppressor by downregulating the expression of HIF-1α to combat breast cancer in an animal model." (PMID 35592530, 2022). "From analyses of the same three patient breast cancer datasets, we find HIF1A transcripts and its transcriptional targets, CAIX and VEGFA, and G3BP1 (but not NRF2) are all significantly higher in breast cancers that exhibit gain of function or amplified KRAS." (PMID 34294889, 2022). "WWOX knockdown in the MCF7 breast cancer cell line led to the upregulation of HIF1α glycolytic genes." (PMID 36271927, 2022). "Several potential approaches for targeting HIF-1α in breast cancer are described and summarized below." (PMID 36003773, 2022). "This study reveals that plumbagin exerts anticancer activity in breast cancer cells by inhibiting HIF-1α activity under hypoxic conditions." (PMID 36080483, 2022). "This study not only corroborates the oncogenic roles of DLEU1, HIF-1α, and CKAP2, but also justifies the potential of targeting these molecules in the treatment of breast cancers, particularly those associated with higher malignancy and worse prognosis." (PMID 35853854, 2022).
breast cancer (continued). "Although the relationship between HIF-1α and drug resistance in breast cancer has been emphasized above, the mechanisms by which it induces resistance in chemotherapy, endocrine therapy, and targeted therapy remain to be clarified." (PMID 36003773, 2022). "Concordantly, elevated levels of succinate or fumarate stabilizing HIF-1α are able to reprogram breast cancer cells into a stem-like state." (PMID 35158815, 2022). "Hypoxia increases the motility of breast cancer cells, and this response is lost when expression of HIF-1α and HIF-2α is silenced." (PMID 35642641, 2022). "TRPC1 mediates hypoxia responses also in breast cancer cells, where HIF-1α promoted its upregulation." (PMID 35806388, 2022). "This review mainly discusses the role of HIF-1α in the drug-resistant breast cancer and highlighted the potential of HIF-1α -targeted therapy." (PMID 36003773, 2022). "Here, MCT4 expression is upregulated by both a stiffer ECM and hypoxia in breast cancer through transcriptional activation of MCT4 by the binding of HIF-1α to hypoxia response elements." (PMID 36140753, 2022). "Consist with these researches, this study found that the expression of SIAH2 and HIF-1α was enhanced in breast cancer SP cells exposed to hypoxia, along with the increased EMT transformation and VM formation." (PMID 35309179, 2022). "On the other side, lactic acidosis for 24 h or extracellular acidosis for 48 h represses the hypoxia response by the inhibition of HIF-1α synthesis in breast cancer cells." (PMID 36012235, 2022). "HIF-1α regulates PDK1 mediated glycolytic metabolism in liver-metastatic breast cancer cells, revealing a pivotal role in the progression of liver metastasis." (PMID 36076967, 2022). "Accordingly, the involvement of MAPK signaling in the regulation of HIF-1α by IGF-I was observed in breast cancer cells using MEK1/2 inhibitors." (PMID 35158804, 2022). "This study preliminarily explores the mechanism by which HNK interferes with glycolysis in breast cancer cells by inhibiting HIF-1α expression." (PMID 35350760, 2022). "To further investigate the possible role of ATP-HIF-1α signaling in breast cancer chemoresistance, we detected the expression of HIF-1α in MDA-MB-231, MCF-7, and MCF-10A (normal breast epithelial cells)." (PMID 35236823, 2022). "lncRNA HIF-1α-stabilizing long noncoding RNA (HISLA) has been reported to suppress the interaction of PHD2 and HIF-1α to inhibit the hydroxylation and degradation of HIF-1α, leading to the regulation of aerobic glycolysis of breast cancer cells." (PMID 39280890, 2022). "LncRNA HIFAL is essential for maintaining HIF-1α triggered transcription under hypoxia condition and glycolysis in breast cancer cells." (PMID 36182907, 2022). "For example, a clinical trial of 187 patients with T2-4 N0-1 breast cancer found that overall response to epirubicin and tamoxifen treatment decreased with increased tumor HIF-1α." (PMID 36003773, 2022). "In another study on the impact of tumor-associated macrophage activity on breast cancer cell lines (MDA-MB-231, MDA-MB-468, BT-474, MCF-7), silencing the HIF-1α isoform resulted in reduced glucose uptake and lactate production." (PMID 36139678, 2022). "As a result, stabilized HIF-1α activates Shh (sonic hedgehog) signaling to promote tumorigenesis and stem formation in breast cancer cells." (PMID 36499136, 2022). "In this study, we found that HNK reduced the accumulation of the HIF-1α protein in breast cancer cells by improving the ubiquitination degradation of HIF-1α." (PMID 35350760, 2022). "In breast cancer cell lines, it has been shown that during hypoxia, HIF-1α expression stabilizes after 4–16 h, then gradually decreases, whereas HIF-2α stabilizes after 24 h." (PMID 36057753, 2022). "For instance, hypoxia in breast cancer induces HIF-1α expression and promotes the effect of PKM2 on glycolysis through upregulation of YTHDF1, triggering cancer cell growth and metastasis." (PMID 35794625, 2022).
breast cancer (continued). "At present, there are only a few studies on metal nanocarriers targeting HIF-1α in breast cancer and SPION has certain toxicity." (PMID 36532768, 2022). "As expected, the abundance of HIF-1α protein was significantly increased in breast cancer cells under hypoxic conditions, and the expression of ACE2 was also significantly upregulated." (PMID 36335375, 2022). "G6PD acts as an oncogene in many types of cancers and Nrf2 promotes breast cancer cell migration via up-regulation of G6PD/HIF-1α/Notch1 axis." (PMID 35818395, 2022). "We demonstrated the direct interaction between DLEU1 and HIF-1α in breast cancer cells, the impact of knocking down each on the expression of CKAP2, and their separate yet positive correlation with CKAP2 level in breast cancer." (PMID 35853854, 2022). "On the other hand, HIF-1α directly activates transcription of CD47 gene in hypoxic breast cancer cells." (PMID 36014432, 2022). "In breast cancer, it has been shown that HIF-1α, in concert with G protein-coupled estrogen receptor 1 (GPER), transcriptionally upregulates VEGF expression in hypoxic CAFs to promote endothelial tube formation." (PMID 35884382, 2022). "In breast cancer, circ_0000977 binds to miR-153 to counteract the inhibition of hypoxia-inducible factor 1-α (HIF1A) and a disintegrin and metalloproteinase domain-containing 10 (ADAM10)." (PMID 35464462, 2022). "TCGA analysis of 1104 breast cancer samples showed a significant positive correlation between HIF-1α and CKAP2 expression levels." (PMID 35853854, 2022). "High expression of HIF1α predicts early recurrence and metastasis of breast cancer, which is inversely correlated with survival." (PMID 36473847, 2022). "A positive correlation of expression of YAP and WWTR1 with expression of HIF1A was detected in breast cancer patients, with particularly high expression of all three genes in basal-like tumors." (PMID 36077517, 2022). "HIF-1α upregulation in breast cancer cells inhibited the Warburg effect, enhanced mitochondrial oxidative phosphorylation, induced the accumulation of reactive oxygen species (ROS), and contributed to tumor cell apoptosis." (PMID 35090526, 2022). "It has been demonstrated that hypoxia decreases ER and PR levels in breast cancer, suggesting a relation between HIF-1α expression and resistance to hormonal therapy." (PMID 36358811, 2022). "This study provides evidence that plumbagin significantly downregulated mRNA expression of VEGF-A and VEGF-R2, key HIF-1α targets, indicating that plumbagin inhibited HIF-1α-mediated transcription in MCF-7 breast cancer cells under hypoxic conditions." (PMID 36080483, 2022). "For example, HMGB1 can regulate HIF-1α expression in breast cancer cells through the PI3K/AKT signaling pathway." (PMID 35637945, 2022). "In particular, IHC staining showed that HIF-1α expression was positively associated with clinical TNM stages and grades of breast cancer." (PMID 35236823, 2022). "The in vivo data strongly suggests that HIF-1α plays a significant role in breast cancer metastasis." (PMID 36003773, 2022). "In this study, we address the role of tumour hypoxia, detected by HIF-1α IHC or hypoxic gene-expression signatures, in relation to outcome and benefit of RT in a large, randomised trial of postoperative RT in early breast cancer." (PMID 35140341, 2022). "One possible explanation for the glycolytic phenotype of ER+ breast cancer cell lines is that ERα mediates the transcriptional activation of the hypoxia inducible factor-1α (HIF-1α)." (PMID 36182907, 2022). "Taken together, these results suggest that breast cancer cell-derived exosomal EPHA2 promotes angiogenesis by activating the downstream AMPK- HIF1-α pathway through Ephrin A1-EPHA2 forward signaling." (PMID 35673569, 2022). "For example, increased activity of the PI3K/Akt/mTOR pathway observed in breast cancer can lead to an increased level of HIF-1α." (PMID 36139678, 2022).
breast cancer (continued). "Previous reports have shown that inhibition of HIF-1α decreased the proportion of breast cancer stem cells in xenografts and that a hypoxic state induced more malignant traits in these cells." (PMID 35626715, 2022). "The modulation of glucose-6-phosphate dehydrogenase (G6PD)/ HIF-1α expression by Nrf2 is consequently involved in the Notch1 pathway-mediated regulation proliferation, migration, and invasion of breast cancer." (PMID 36289931, 2022). "We have previously shown, on the molecular level, that in hypoxic breast cancer cells ER-expression diminishes as HIF-1α accumulate." (PMID 35140341, 2022). "High expression of HIF1α predicts early recurrence and metastasis of breast cancer and is inversely correlated with survival in patients." (PMID 36473847, 2022). "The findings suggest that the Hsp90 inhibitor AT-533 inhibits tumor angiogenesis by inhibiting breast cancer growth and blocking HIF-1α/VEGF/VEGFR-2-mediated signaling, thereby, triggering an antitumor response in breast cancer." (PMID 35805939, 2022). "One of these cytokines is macrophage migration inhibitory factor (MIF), which is a direct target gene of HIF-1α and a hypoxia-induced gene in colon and breast cancer cells." (PMID 36496973, 2022). "As reported, miR-100-5p inhibits angiogenesis by suppressing mTOR/HIF-1α/VEGF signaling in breast cancer cells, which was also validated in the endothelial cells in the present study." (PMID 35241153, 2022). "In mammary cancer, HIF1A expression is positively correlated with stiffer tissues in mammary cancer patients." (PMID 35205794, 2022). "To date, just a few studies have demonstrated the existence of statistically significant relations between the expression of HIF-1α and pCR in breast cancer after neoadjuvant chemotherapy based on anthracyclines and taxanes." (PMID 36358811, 2022). "Conditioned media from another breast cancer cell line—MCF7 (MCF7 CM)—also induced an increase in the expression of both HIF-1α protein and HIF-1α mRNA in BM-MSCs." (PMID 36230633, 2022). "The knockdown of Nrf2 overexpression decreased HIF-1α mRNA levels and reduced breast cancer cell proliferation." (PMID 35571115, 2022). "Hypoxia-induced occupancy of the ANGPTL4 and PDK1 HREs by TRIM28, KU70, KU86, DNA-PKcs, and HIF-1α was also observed in SUM159 human breast cancer cells." (PMID 35031618, 2022). "To obtain clues about the potential clinical implications of miR-935/HIF1A axis dysregulation in triple-negative 3D cultures, we performed an overall survival analysis using Kaplan–Meier analysis in a cohort of breast cancer patients." (PMID 35626094, 2022). "The relation between the expression of HIF-1α and pAKT was examined by immunohistochemistry in breast cancer in a single study." (PMID 36358811, 2022). "Mechanistically, HMGB1 can promote angiogenesis and migration of breast cancer through the PI3K/AKT/HIF-1α pathway." (PMID 35637945, 2022). "Through downregulating SIAH2 and HIF-1α, sinomenine can inhibit epithelial-mesenchymal transition process of breast cancer SP cells." (PMID 35309179, 2022). "In summary, it can be concluded that HIF-1α can lead to breast cancer resistance to endocrine drugs and cytotoxic drugs through upregulation of autophagy." (PMID 36003773, 2022). "HIF‐1α drives glycolytic metabolism in metastatic breast cancer cells and promotes metastasis and colonization of cancer cells to the liver." (PMID 34914196, 2022). "According to Mangraviti and his colleagues, ACF can inhibit transcriptional activity of HIF-1α not only in brain cancer but also in cholangiocarcinoma (SK-ChA-1), ovarian (A2780), or breast cancer (MCF-7) cell lines." (PMID 36014432, 2022). "The main overexpressed isoform in breast cancers is HIF-1α which is believed to be more involved in glucose metabolism." (PMID 36139678, 2022).